OR2T33 (olfactory receptor family 2 subfamily T member 33)
Description:
Odorant receptor.
Synonyms: OR1-56; OR2T32
Tractability: Antibody: UniProt places it where antibodies can reach, with medium confidence; UniProt predicts a signal peptide or a membrane-spanning region; its Gene Ontology location is reachable by antibodies, with medium confidence.
Gene: Protein-coding gene on chromosome 1 (248,269,917 to 248,277,976, reverse strand). Ensembl gene ENSG00000177212.
Subcellular location: Cell membrane
Pathways (Reactome):
Sensory Perception: Expression and translocation of olfactory receptors
Gene Ontology:
Molecular function: olfactory receptor activity; G protein-coupled receptor activity
Biological process: detection of chemical stimulus involved in sensory perception of smell; G protein-coupled receptor signaling pathway
Cellular component: plasma membrane; membrane
Genetic constraint (gnomAD): Loss-of-function variants: 11 observed, 13.58 expected, observed/expected ratio (o/e) 0.81, 90% interval 0.51 to 1.34. The upper end of that interval is the gene's LOEUF score, 1.34, which puts it in group 5 of 6, group 1 being the genes least tolerant of losing a copy. Missense variants: 276 observed, 339.49 expected, observed/expected ratio (o/e) 0.81, 90% interval 0.74 to 0.9. Synonymous variants: 103 observed, 129.03 expected, observed/expected ratio (o/e) 0.8, 90% interval 0.68 to 0.94.
Homologues: Orthologues: dog OR2T15 (75% identical), dog OR2T20 (75% identical), dog OR2T24 (75% identical), dog OR2T13 (74% identical), mouse Or2t44 (72% identical), rat Olr1454 (70% identical), rat Or2t44 (70% identical), rat Or2t44b (69% identical). Paralogues in human: OR2T12 (95% identical), OR2T8 (91% identical), OR2M2 (56% identical), OR2M3 (55% identical), OR2M5 (54% identical), OR2M7 (54% identical), OR2V2 (54% identical), OR2M4 (54% identical), OR2V1 (54% identical), OR2T2 (53% identical), OR2T35 (53% identical), OR2T1 (53% identical), and 80 more.